DNAJC25-GNG10 (DNAJC25-GNG10 readthrough)
Gene: Protein-coding gene on chromosome 9 (111,631,386 to 111,670,229, forward strand). Ensembl gene ENSG00000244115.
Genetic constraint (gnomAD): Loss-of-function variants: 9 observed, 6.31 expected, observed/expected ratio (o/e) 1.43, 90% interval 0.82 to 1.92. That is too few expected variants to judge how well the gene tolerates losing a copy. Missense variants: 146 observed, 123.61 expected, observed/expected ratio (o/e) 1.18, 90% interval 1.03 to 1.36. Synonymous variants: 72 observed, 53.91 expected, observed/expected ratio (o/e) 1.34, 90% interval 1.1 to 1.62.